RNU6-928P (RNA, U6 small nuclear 928, pseudogene)
Gene: Small nuclear RNA gene on chromosome 17 (66,638,271 to 66,638,374, forward strand). Ensembl gene ENSG00000252685.
Homologues: Orthologues: chimpanzee U6 (98% identical), macaque U6 (92% identical), guinea pig U6 (67% identical), dog U6 (62% identical), mouse Gm56224 (59% identical). Paralogues in human: RNU6-24P (79% identical), RNU6-1094P (78% identical), RNU6-1243P (78% identical), RNU6-43P (78% identical), RNU6-527P (78% identical), RNU6-652P (78% identical), RNU6-97P (78% identical), RNU6-497P (77% identical), RNU6-655P (77% identical), RNU6-727P (77% identical), RNU6-884P (77% identical), RNU6-1060P (76% identical), and 1282 more.